MMP2 (matrix metallopeptidase 2)
Diseases named in the same sentence as MMP2 in open-access papers (continued):
Sharing a sentence is not in itself a finding about the gene and the disease.
tumor (continued). "Over the last decades it has been extensively reported that tumor associated macrophages are able to promote tumor cell migration thought secretion of matrix-remodeling proteins, cytokines and chemokines (e.g. MMP-2, MMP-9, TNF-α, VEGF, TGF-β, EGF)." (PMID 29728948, 2018). "Our data corroborate other studies in which MMP-2 downregulation in cancer cells and Mmp2-deficient mice show reduced angiogenesis and tumor growth." (PMID 29713337, 2018). "MMP-2 and -9 are type IV collagenase/gelatinase, and their expression is associated with aggressive tumor phenotypes and poor prognosis." (PMID 29356905, 2018). "The activation of MMP-2 has been shown to be a crucial step in tumor invasiveness and is associated with more aggressive phenotypes." (PMID 30359388, 2018). "Among these are two highly associated with tumor dissemination and invasiveness: MMP-2 (aka gelatinase A) and MMP-9 (aka gelatinase B), which degrade type IV collagen and gelatin substrates." (PMID 28633655, 2017). "Immunohistochemical analysis demonstrated that the inhibition of tumor growth and metastasis was associated with activation of Bax, cleaved caspases-3 and -9, and down-regulation of Bcl-2, MMP-2 and -9, NF-κB and IκBα." (PMID 28751740, 2017). "Bone marrow-derived cells adhere to the cross-linked type IV collagen to promote the generation of MMP2, which, in turn, facilitates the degradation of collagen, thereby recruiting metastatic tumor cells to colonize the target organs." (PMID 28356139, 2017). "Among the MMP genes, gelatinase A, encoded by the MMP2 gene, has been specifically correlated to tumor pathogenesis." (PMID 29069837, 2017). "Stable MMP2/9 up-regulation was observed in MG63 cells treated with ADSC-conditioned medium, indicating that MMP2/9 are associated with tumour promotion in vitro and in vivo." (PMID 28423603, 2017). "It is well documented that MMP-2 is implicated in tumor invasion and metastasis, which is also confirmed in some publications." (PMID 26956728, 2016). "The importance of MMP-2 (-1306) gene polymorphism in the susceptibility of various tumours has been shown in numerous studies." (PMID 27051552, 2016). "Numerous studies have also been carried out to look for an association between the MMP-2 -1306 C/T polymorphism and risk of other human tumours, but the results remain controversial." (PMID 27051552, 2016). "A recent study reported that high baseline plasma levels of matrix metalloproteinase 2 (MMP2) are associated with prolonged tumor control and patient survival after bevacizumab treatment." (PMID 26243272, 2016). "Homozygosity for the MMP-2 -1306 T allele was associated with markedly different patient survival depending upon tumour ER status." (PMID 27051552, 2016). "Western blotting demonstrated that levels of the tumor invasion and metastasis-associated proteins, MMP2 and MMP7, were increased or decreased in miR-520g overexpressing or downregulated EOC cells, respectively." (PMID 27049921, 2016). "To find further evidence for this association, we assessed the distribution of active MMP2 and αvβ3 on microregional level in U87 tumor cross sections." (PMID 26923459, 2016). "With reference to the microarray meta-analysis of the EOC tumours, the endogenous expression of MMP2 in the Mes subtype was found to be the highest, suggesting that MMP2 is a mesenchymal-associated MMP in EOC." (PMID 26887977, 2016). "For patients with ER positive tumours, the MMP-2 TT genotype was associated with a trend for very good survival (10/10, 100%) compared to the CC or CT genotypes (130/157, 83%; p = 0.16)." (PMID 27051552, 2016). "The aberrant high expression of MMP-2 was closely associated with tumor differentiation, the depth of invasion, lymph node metastasis, and tumor stage." (PMID 27907907, 2016). "A reduction in tumor growth and vascularization has been observed after transplantation of tumor cells into either MMP2 or MMP9 deficient mice, compared to wild-type mice." (PMID 26979530, 2016).
tumor (continued). "The inverse correlation of MMP-2 and miR-328 was also observed in tumor specimens, and MMP-2 expression was linked to tumor metastasis." (PMID 25605016, 2015). "A majority of malignant tumours express MMP2; the expression of which is associated with the degree of malignancy, tumour angiogenesis, invasiveness and metastasis." (PMID 25671640, 2015). "In summary, we designed and tested the efficacy of a tumour-targeted CPP with an MMP2 cleavage site in delivering plasmid DNA encoding hTERT-specific siRNA." (PMID 25671640, 2015). "The aim of this study was to demonstrate the expression (tumour cell positivity as well as expression intensity) of proteins associated with the metastatic potential of mammary gland carcinomas, i.e., MMP-2 and E-cadherin." (PMID 27486511, 2015). "The MMP-2, -7, and -9 are thought to be associated with tumor invasion, metastasis, and angiogenesis." (PMID 26699938, 2015). "The decline of NF-κB, a critical metastatic regulator, caused apparently reduced protein level of MMP-2 which is responsible for the degration of basement membranes and stromal extracellular matrix and is of pivotal importance in tumour metastasis." (PMID 26081366, 2015). "In particular, MMP-2 and MMP-9 (also known as gelatinase-A and gelatinase-B) are most linked to the malignant phenotype of tumor cells and are commonly used as markers of malignant cancer." (PMID 25922552, 2015). "Tumor buds overexpress protein markers associated with tumor cell migration and invasion such as matrix metallopeptidase 2 (MMP2), MMP9 and cathepsinB (CTSB)." (PMID 25884643, 2015). "In UC, the positive association between MMP2 expression and tumor stage and histological grade has been reported based on testing small batches of UBUC without systematic evaluation." (PMID 26307680, 2015). "Usually the stromal expression of MMP-2 was linked with the expression in tumor cells, and their expression was analyzed and graded together as a positive expression." (PMID 25816052, 2015). "Staining of mTOR in the tumor center correlated with p-mTOR (r = 0.195, p = 0.028), and there was a positive association MMP2 with MMP9 at the invasive front (r = 0.214, p = 0.015)." (PMID 26652716, 2015). "Degradation of the ECM is an important process associated with tumor invasion, in which MMP-2 play a critical role." (PMID 24715095, 2014). "In contrast, MMP2 mRNA (that hybridized to the anti-sense oligonucleotide, but not to the sense oligonucleotide) was found in the majority of tumor-associated stromal cells." (PMID 25326065, 2014). "Previous studies have indicated that MMP2 is expressed in a variety of tumor cells, and is associated with tumor cell growth, invasion and metastasis." (PMID 25013467, 2014). "In particular, MMP-2 and -9, also known as gelatinase A (72 kDa) and B (92 kDa), respectively, are most often associated with the malignant phenotype of tumor cells." (PMID 24520285, 2014). "Studies of matrix metalloproteases (MMPs) in invasive cancers have indicated that MMPs play an important role in the development of tumor metastases, among which MMP-2 and MMP-9 are particularly associated with distant dissemination of malignant tumors." (PMID 25496480, 2014). "Although several MMPs have been associated with tumor progression, particular attention has been focused on MMP-2 and membrane type-1 MMP (MT1-MMP)." (PMID 25317077, 2014). "Lower baseline angiopoietin-2 (Ang-2) and higher baseline matrix metalloproteinase-2 (MMP-2) levels were identified by both platforms as statistically significantly associated with tumor response." (PMID 25100134, 2014). "MMPs, in particular MMP-2 and -9, are markedly associated with this process due to their capacity to degrade the extracellular matrix, which promotes tumor invasion." (PMID 25295091, 2014).
tumor (continued). "We have found the significant associations between decreased MMP-2 expressions in inflammatory cells and distant metastases as well as between tumor invasion and reduced expression of TIMP-2 in inflammatory interstitium." (PMID 24395652, 2014). "It is widely believed that the effect of MMP2 on the extracellular matrix is closely associated with tumor invasion and metastasis." (PMID 25013467, 2014). "Another hematopoietic cytokine secreted by HNSCC tumor cells, G-CSF, has been shown to increase the invasiveness of tumors via upregulation of MMP-2 and is associated with a worse prognosis in patients." (PMID 24698959, 2014). "Platelet depletion led to reduced tumor hypoxia and Met receptor activation and was associated with a decreased release of MMP-2, 9, PAI-1, VEGF, and TGF-β." (PMID 24606812, 2014). "Among the members of this family of proteins family, gelatinase A (MMP-2) is implicated in local tumor invasion and metastasis." (PMID 25208219, 2014). "MMPs, particularly MMP-2 and -9, are associated with this process due to their capacity to degrade the extracellular matrix, promoting tumor invasion." (PMID 25120638, 2014). "Taken together, our data suggest the enhanced expression of invasion associated MMPs specifically of MMP-2, -9, and -26, concomitant a stromal activation as mechanisms behind the GM-CSF driven tumor cell invasion." (PMID 23634280, 2013). "Because serum concentration of MMP-2 was significantly elevated in tumor patients, MMP-2 was suggested as a diagnostic and prognostic marker." (PMID 24023566, 2013). "Taken together, the data presented here describe GM-CSF as factor driving tumor progression and invasion via enhancing the expression of invasion associated MMPs, such as MMP-2, -9 and, -26, and shed some light on mechanisms of GM-CSF driven tumor progression." (PMID 23634280, 2013). "Recent research has found many other roles that MMP2 plays in tumor progression: MMP2 is linked to EGFR and integrin signaling, which lead to cell migration, and the switch to an angiogenic phenotype in an animal model (Epithelial–Mesenchymal Transition)." (PMID 23936390, 2013). "The effects of GSK3β inhibition on tumor invasion, susceptibility to gemcitabine, MMP-2 expression and FAK phosphorylation were observed in tumor xenografts." (PMID 23408967, 2013). "In HCC, loss of E-cadherin expression is associated with tumor invasiveness, metastasis, and prognosis Matrix metalloproteinases-2 (MMP-2) are also involved in EMT in HCC." (PMID 22949882, 2012). "Integrin αvβ3 mediates migration into the fibrin-rich cancer stroma and furthermore can associate with MMP-2, thus enabling ECs to maintain the BM in the sol state and to promote tumor cell invasion." (PMID 21941547, 2012). "Expression of MMP-9 and MMP-2 has been implicated in the development and progression of many neoplasias, such as prostate, colorectal and lung cancer." (PMID 22695075, 2012). "In our recent immunohistochemical study, we found that EMMPRIN expression in SACC was positively-associated with tumor perineural and perivascular invasion, and that MMP-2 and MMP-9 were expressed both in the tumor and stromal compartments." (PMID 22200897, 2012). "High tumour and stromal MMP-2 and MMP-9 expression was significantly associated with positive lymph node status." (PMID 23107277, 2012). "It was further stated by Enloe and Jay that inhibition of CD155 by RNAi caused a decrease in tumour invasion in part through reduced activity of matrix metalloproteinase-2 (MMP-2), a known factor in GBM invasion." (PMID 22363471, 2012). "In this study, our goals were to investigate the precise role of HSA/TIMP-2 in anti-tumor activity associated with angiogenesis and further define in vivo molecular links between anti-angiogenesis and the modulation of MMP-2." (PMID 22545131, 2012). "This study is the first report of the in vivo mechanism underlying anti-tumor activity and anti-angiogenesis associated with MMP-2 modulation via TIMP-2 protein." (PMID 22545131, 2012).
tumor (continued). "Intriguingly, endothelial-derived MMP-2 has been implicated in promoting cancer cell extravasation, thereby increasing the tumor’s metastatic potential." (PMID 22666456, 2012). "Some members of the matrix metalloproteinase (MMP) family like MMP-2 and -9 are known to be associated with tumor growth and metastasis because of their capacity to degrade collagen IV, the major ECM component." (PMID 21857898, 2011). "The specific importance of the gelatinases MMP-2 and MMP-9 to tumour progression has been delineated in an in vivo study, where combined MMP-2/MMP-9 deficiency in mice significantly impaired tumour angiogenesis and invasion." (PMID 21559216, 2011). "Basic fibroblast growth factor (bFGF), VEGF and MMP-2 are some of these important molecules underlying tumor angiogenesis and growth." (PMID 24281074, 2010). "The several lines of evidence reveal that Akt, which functions downstream of PI3K, is associated with the invasiveness and motility of tumor cells and the secretion of MMP-2." (PMID 20170548, 2010). "In these studies, the increased MMP-2 activity in tumor cells expressing Furin was linked to the increased activity of MT1-MMP, which is processed by Furin." (PMID 20404912, 2010). "MMP-2 is known to be induced in tumour stroma cells, mainly by tumour-associated fibroblasts in response to the presence of tumour cells or tumour-produced factors." (PMID 20723242, 2010). "Since BSP and MMP-2 are associated with tumor progression, the potential modulation of proMMP-2 activity by BSP is particularly relevant to tumor metastasis." (PMID 19386107, 2009). "In our study, the activated NF-κB and consequently, enhanced MMP-2 most likely exert an anti-apoptotic action, promoting the survival of defective cells, thereby causing tumor growth in HCM cells." (PMID 19816602, 2009). "MMPs have traditionally been associated with tumor cell invasion and metastasis, in particular MMP-2 and its activator MT1-MMP." (PMID 19386107, 2009). "RECK encodes a membrane-associated MMP regulator protein that is able to suppress tumor invasion and metastasis by negatively regulating MMPs involved in carcinogenesis, namely: MMP-2, MMP-9 and MMP-14 (MT1-MMP)." (PMID 19144199, 2009). "The authors reported that, in three-dimensional environments, E-cadherin deficiency indeed led to a loss of intercellular adhesion and triggered tumor cell invasion by MMP-2 and MMP-9 driven matrix degradation." (PMID 17254360, 2007). "Smaller tumors were formed when FaDu tumor cells were co-injected with MT1-MMP deficient fibroblasts as compared either MMP-2 null (80% smaller) or MMP-9 null (80% smaller) or WT fibroblasts (92% smaller)." (PMID 16515711, 2006). "This is reinforced by a recent study demonstrating the influence of tumour associated fibroblasts on MCF-7 tumour cells to activate MMP-2 in vitro and increase tumour size in vivo." (PMID 16430785, 2006). "Alternatively, an enhanced release of MMP-2, an enzyme which is sequestered on the cell surface and on collagens in the matrix, can be expected when the tumour volume and the associated desmoplastic stroma are reduced under effective chemotherapy." (PMID 12698191, 2003). "This active MMP-2 can associate with the cell surface of tumour cells and fibroblasts and is used in the processes of tissue remodelling and invasion." (PMID 10408832, 1999). "Interestingly, while MMP-2 deficiency reduced tumor infiltration into brain parenchyma, it promoted perivascular invasion, with tumor cells migrating along blood vessels." (PMID 40265458, 2025). "The LyP-1-modified nanosystem containingendostatin showed improved effectiveness in fighting against KYSE-30cells by directly attacking tumor lymphatics, causing nucleus rupture,degrading mitochondria, reducing cell growth and movement, and inhibitingVEGF-C and MMP2 expression." (PMID 40184281, 2025).
tumor (continued). "In vivo experiments demonstrate that suppressing HIF-1α protein expression reduces the growth rate of subcutaneously formed tumors and decreases the expression levels of proteins associated with the P-PI3K/P-AKT, SOX2/OCT4, and MMP2/MMP9 pathways within the tumor." (PMID 39781344, 2025). "However, the loss of activated MMP-2 expression the tumour cells interacts with the components of the new onco-sphere causes the tumour cells to go into a period of dormancy or latency." (PMID 41373503, 2025). "Thus, research has increasingly focused on designing selective inhibitors that target specific MMPs associated with tumor progression, notably MMP-2, MMP-9, and MMP-14." (PMID 40265458, 2025). "Thus, increased levels of MMP-2 are associated with an aggressive tumour phenotype in carcinomas of the oesophagus, pancreas, prostate, lung and ovary." (PMID 40724562, 2025). "Doxorubicin (DOX) was conjugated to the HPMA copolymer through a lysosomal cleavable linker and tumor-targeting and -penetrating peptide iRGD, which is selectively cleaved by MMP-2, an enzyme overexpressed in the prostate cancer microenvironment and closely linked to tumor progression." (PMID 39852748, 2025). "In addition to its effects on NF-κB, metformin also impacted the expression of matrix metalloproteinase-2 (MMP-2), a protein associated with tumor invasion." (PMID 40277915, 2025). "A previous study showed that HMGB1 could bind to RAGE, activate the MAPK signaling pathway, and then cause the activation of matrix proteases MMP9 and MMP2, degraded extracellular matrix, and promote tumor invasion and metastasis." (PMID 38577597, 2024). "Additionally, the expression levels of MMP2, influenced by the regulation in associated pathways, have been shown to either promote or inhibit tumour cell invasion in PCa." (PMID 39336161, 2024). "Then, in a weak acidic environment, the DEAP molecules underwent protonation, causing the nanostructure to swell and allowing the MMP-2, which was highly expressed in the tumor matrix, to enter and cut the peptide substrate, further breaking down the NPs and releasing the DPPA-1 and NLG919." (PMID 39339228, 2024). "They showed that the trypsin inhibitor induced necrosis in tumour tissue, simultaneously suppressing the expression of pivotal genes associated with angiogenesis, such as matrix metalloproteinase genes (MMP-2, MMP-9) and vascular endothelial growth factor (VEGF)." (PMID 39247112, 2024). "Furthermore, MMP-2 expression in OSCC showed significant associations with tumor invasion depth, tumor-node-metastasis stages, and lymph node metastasis." (PMID 38673838, 2024). "Other studies have implicated MMP2 with tumor metastasis to other organs, including the brain." (PMID 39057065, 2024). "MMP2 expression is closely associated with tumor cell migration and prognosis." (PMID 39519855, 2024). "Additionally, studies have shown that MMP-2 expression is increased in various cancers, including lung cancer, and is closely associated with tumor cell growth and migration." (PMID 39451714, 2024). "It is worth noting that compound 1, on the contrary, caused an increase in the expression of MMP-2 against the background of inhibition of Hh signaling, which may aggravate the process of tumor progression." (PMID 39274874, 2024).